CDC42 (cell division cycle 42)
Diseases named in the same sentence as CDC42 in open-access papers (continued):
Sharing a sentence is not in itself a finding about the gene and the disease.
tumor (continued). "For three genes—CDC42, PLAC8, and RHOA—for which no information about the variant is available in some tumor types, comparison between different datasets or tumor entities may suggest which miR-185 version is responsible for their regulation." (PMID 36287119, 2022). "In benign T and B cells, WASp is a tumor-suppressor protein, however it acts as a tumor activator in malignant lymphocytes, since the lack of WASp leads to an imbalance of CDC42/MAPK and NF-κB/AP-1 signaling pathways, which is important for the development of cancer." (PMID 35371070, 2022). "Furthermore, its downstream regulator Cdc42 induces tumor metastasis, and thus, both CD47 and Cdc42 may be considered potential therapeutic targets to control NSCLC." (PMID 34367975, 2021). "Deletion of cdc42 and rac1 in a haploid strain did not result in tumor formation in maize." (PMID 33924947, 2021). "Accordingly, we measured the proliferation, migration, RhoA activation, the mRNA and protein levels of hypoxia inducible factor-1alpha (HIF-1α) and three small G-proteins, Rac1, cdc42 and RhoA in a panel of five human tumor cell lines under normoxic and hypoxic conditions." (PMID 28562340, 2017). "We tested for an association of CDC42 with intrinsic subtype using the Gallen IHC system, whereby Luminal A tumours are defined as ER+, Ki67-low, Luminal B are ER+ and either Ki67-high or HER2+, HER2 tumours are ER−, HER2+, and Negative tumours are ER−, HER2−." (PMID 28451966, 2017). "Finally, AZA197, another recently developed Cdc42 inhibitor which appears not to inhibit Rac1 activity has shown some efficacy in reducing tumor size in a xenograft model of colon cancer." (PMID 27104658, 2016). "When taken together with the ability of restoration of c-Cbl function via Cdc42 knockdown to inhibit mammosphere formation and tumour initiation in vivo, it appears that such manipulations modulate the biology of both TICs and of the bulk population of BLBC tumour cells." (PMID 23606532, 2013). "However, the effects of Cdc42 overexpression on mammary gland development and the stochastic process of tumor formation in vivo have not been previously investigated due to a lack of Cdc42-overexpressing mouse models." (PMID 24074261, 2013). "In contrast, most probiotics did not affect the acetylation of CDC42 K153, such as Streptococcus thermophiles, Lactobacillus rhamnosus, Lactobacillus plantarum, and Lactobacillus paracasei, and these bacterial species have been shown to inhibit tumor growth of CRC." (PMID 36812247, 2023). "In addition to ROS, cytokines or physiological factors enriched in the tumor microenvironment, such as the migration stimulating factor (MSF), a genetically truncated N-terminal isoform of fibronectin, can also induce mitophagy in tumor stromal cells by activating TGF-β and CDC42- NFκB signaling." (PMID 38067169, 2023). "Thus, this system might be likely to reflect the activation of endogenous Rac1 mainly in the patients’ tumor tissues, although activation of other Rac members, such as Rac2 and Rac3 and/or Cdc42 cannot be ruled out." (PMID 35110666, 2022). "In addition, Cdc42 signaling through its effectors MRCKα and β can also generate actomyosin contractility, through direct phosphorylation of MLC29-11 and activation of Cdc42 can also promote the formation of matrix-degrading invadopodia in CAFs leading to enhanced tumor cell invasion." (PMID 27248291, 2017). "However, our understanding of the mechanisms by which aberrant expression of Cdc42 disrupts mammary gland morphogenesis and facilitates tumor formation and progression in vivo has been limited until now due to a paucity of in vivo mouse models of Cdc42 overexpression and hyperactivation." (PMID 24074261, 2013). "In our current study, we found that the overexpression of Porf-2 reduced the activated Rac1 levels in tumor cells, but not Cdc42, demonstrating that Porf-2 acts as a Rac1-specific GAP in tumor cell migration, which is consistent with previous reports." (PMID 32676454, 2020).
tumor (continued). "Cdc42 knockdown was even more effective at preventing tumour generation by HCC1954 (Basal-A with HER2 amplification) and HCC70 (Basal-A) cells, and no cells expressing shRNA for Cdc42 generated tumours even when 10,000 cells were transplanted." (PMID 23606532, 2013). "Cdc42 expression level was not significantly different between grade I and grade III tumours (data not shown)." (PMID 12237774, 2002). "Indeed, among the most upregulated genes in FAT4 knockdown cells we found ARHGEF6, encoding for the guanine nucleotide exchange factor αPIX that activates Rac1 and Cdc42 GTPases and ARHGDIB, a negative modulator of the RhoA tumor suppressor." (PMID 39478125, 2024). "We presented here that Rac1 activity but not RhoA or Cdc42 was increased significantly by PA treatment through CD36-Src-Akt signaling pathway, suggesting that Rac1 participated in triggering actin-remodeling and promoting LUAD tumor metastasis." (PMID 37612265, 2023).
infection (91 papers, 2007 to 2025). The state of being infected such as from the introduction of a foreign agent such as serum, vaccine, antigenic substance or organism. "Affected CDC42 results in a distinct clinical phenotype with neurodevelopmental, hematologic, and immunologic abnormalities with increased predisposition to infections and malignancies." (PMID 36726976, 2022). "We investigated if the observed loss of infection was a result of Cdc42 knockdown due to Cdc42s’ role in cell cycle progression." (PMID 35746622, 2022). "Our data showed a loss of cell cycle progression in the presence of Cdc42 siRNA; thus, the loss of infection can be in part attributed to cell cycle arrest in addition to Cdc42’s role in filopodia formation." (PMID 35746622, 2022). "The findings reported in this study extend the phenotypic spectrum resulting from CDC42 (p.P34Q) mutation and implies that patients with poor wound healing/recurrent infection can be screened for this germline mutation." (PMID 33672558, 2021). "At this timepoint, only 7–10% of bacteria are intracellular, thus the recruitment of Rac1 and Cdc42 (8.6 ±0.9% and 6.7 ±1.3% respectively) reflects the transient association of these with nearly every invasion-competent EB at 10 minutes post-infection." (PMID 29727463, 2018). "In contrast, infection with shATF4 lentivirus caused 54 ± 3% and 56 ± 11% decreases in total Cdc42 protein levels in cortical and hippocampal neurons, respectively." (PMID 25071442, 2014). "Third, elucidation of the functions of circCDC42 and its encoded protein CDC42-165aa provides insight into the function of circRNAs in regulating inflammatory responses and additional evidence that inhibition of circRNAs controls infection." (PMID 38977695, 2024). "Their research does however confirm that PAK is activated in a type three secretion system (T3SS) dependent manner during the first 30 minutes of infection, and that the expression of a variant of Cdc42 that cannot bind PAK does impede uptake, consistent with our findings here." (PMID 34460869, 2021). "Here we highlight the vital role of Cdc42 for intercalary hyphal growth, as well as involvement of RacA in regulation of hyphal network formation, and demonstrate the consequences of mutations in these genes on plant tissue infection." (PMID 29370294, 2018). "Infection of Caco-2 BBE1 cells causes a ~65% reduction in levels of Cdc42-GTP." (PMID 24600591, 2014). "However, the novel host-directed small molecule inhibitor ML141 may provide an alternative strategy that circumvents statin limitations by selectively targeting CDC42, a key host cell-signaling molecule implicated in invasive infection." (PMID 34959329, 2021). "Although these protein analyses and our studies were performed at different infection times, GTPases family members such as CDC42, RAC1 and RHO were found dysregulated suggesting them as essential players in the infection." (PMID 40396886, 2025). "The expression of C-C motif chemokine ligand 25 (CCL25), CD74, and cell division cycle 42 (CDC42) was also higher in SUS than RES lambs in response to challenge infection." (PMID 40811742, 2025). "Elevated C1P levels were found to benefit the bacterium during infection of myeloid cells and mice, and the sphingolipid disrupts Golgi structure by promoting Cdc42 membrane-binding, PKCα phosphorylation of GRASP55, and JNK phosphorylation of GRASP65." (PMID 38415594, 2024). "To determine the efficacy of chemical inhibition of the Cdc42/Rac pathway in animal infection, we used silkworms, a well-established invertebrate infection model for various fungi, including dermatophytes." (PMID 38952678, 2024). "This was further substantiated by ΔsopB infection, where Cdc42 activity was reduced as compared to wild-type bacteria at 24 hpi." (PMID 36717589, 2023).
infection (continued). "RNA inactivation of cdc-42, a gene encoding the ortholog of the mammalian WASP regulator CDC42, showed similar effects of increased infection symptoms, and such phenotype was observed in a heterozygous cdc-42 mutant." (PMID 37131627, 2023). "Herein we observed increased Rac1 expression in BMDMs infected with L. braziliensis and L. infantum; by contrast, infection by L. amazonensis resulted in increased Cdc42 expression." (PMID 37576604, 2023). "The SILAC results showed that CDC42 acetylation at lysine 153 (K153) was downregulated by approximately 2-fold at 1 h post-infection." (PMID 36812247, 2023). "CDC42 plays a critical role in several cell signaling pathways, and therefore, many pathogens hijack CDC42 to facilitate their infection." (PMID 36812247, 2023). "By contrast, murine macrophages exhibited increased Rac-1 expression after infection with L. braziliensis and L. infantum, while L. amazonensis infection was found to increase Cdc42 expression." (PMID 37576604, 2023). "Treatment with 2-pyridone PIM1 inhibitor was able to significantly downregulate Notch1, Notch2, CTNNB1, and CDC42 in SARS-CoV-2-infected cells at 24 h post-infection (p-value < 0.001)." (PMID 37211584, 2023). "In fact, single knockdown of Cdc42, double-knockdown of Dnm1 and Dnm2 (Dnm1/2) and triple-knockdown (Dnm1/2/Cdc42) significantly blocks infection, suggesting that internalisation of the infectious seed is critical in establishing prion infection." (PMID 38102121, 2023). "In agreement with vimentin reorganization, Cdc42 became enriched around SCVs post wild-type S. Tm infection, whereas it showed diffused distribution in un-infected or ΔsopB S. Tm infected condition." (PMID 36717589, 2023). "This highlighted an indispensability of cdc42 for the insect pathogenicity and virulence of B. bassiana through the normal infection." (PMID 35448625, 2022). "There was a 55% decrease in infection when cells were treated with Cdc42 siRNA for 48 h compared to control infection [17.2% to 38.15%, respectively]." (PMID 35746622, 2022). "We observed a significant decrease in infection when both siRNA and drugs against Cdc42 were used in HaCaT cells." (PMID 35746622, 2022). "We did observe a greater decrease in infection when cells were treated with ML-141 (74%) compared to cells treated with Cdc42 siRNA (55%)." (PMID 35746622, 2022). "Our data shows that Cdc42 depleted cells had significantly less filopodia, lower infection compared to control infection, and decreased overlap between PsVs and EEA1." (PMID 35746622, 2022). "The two measurements demonstrated an important role for Cdc42 in host infection and insecticidal activity of B. bassiana, well in accordance with blocked cuticle infection and greatly attenuated virulence observed in the Δcdc42 mutant." (PMID 35448625, 2022). "The effector primarily targets the GAP domain of ABR to suppress Rac1 and Cdc42, host cell cytotoxicity, bacterial invasion, and filopodium formation at infection sites." (PMID 36219160, 2022). "We show that Cdc42 activity is partially influencing the formation of filopodia and initial infection." (PMID 35746622, 2022). "There was a statistically significant decrease of 59% in colocalization of cells treated with Cdc42 siRNA compared to the control infection." (PMID 35746622, 2022). "The previous studies demonstrate not only a conserved role for Cdc42 in the fungal cell cycle and polar growth but also its special role in filamentous fungal adaptation to host infection." (PMID 35448625, 2022). "Perhaps CDC42 is partaking in the transportation of bacteria-containing vesicles to aid eradicating infection at the timepoint." (PMID 34350128, 2021). "We further identified specific steps of the infection process, at which Rac1 and Cdc42 play a crucial role." (PMID 32645930, 2020).
infection (continued). "We, therefore, surmise that the main reason for reduced infection rates by blocking Cdc42 or Rac1 is reduced virion trafficking in the host cell, caused by the inability of EHV-1 to induce α-tubulin acetylation." (PMID 32645930, 2020). "Cytoskeleton-related genes such as ACTL10 and Cdc42 were overexpressed in basolateral infection compared to apical infection." (PMID 32872518, 2020). "The inhibitory effect of Rac1 and Cdc42 inhibitors was more pronounced in the case of EHV-1 gH4 and EHV-1 gHS440A, where it resulted in an ~80% (Rac1 inhibitor) and ~95% (Cdc42 inhibitor) reduction of infection." (PMID 32645930, 2020). "There is also evidence that Cdc42 plays a major role in wound healing, regarding host defense against infection." (PMID 30323791, 2018). "cdc42 mutants were able to colonize younger host tissue, but the hyphae were fragmented when tillers of the host plant elongated, indicating that Cdc42-mediated intercalary hyphal growth is a key event for systemic infection of the fungus in host plants." (PMID 29370294, 2018). "Perennial ryegrass was inoculated with cdc42/Cdc42-R8 or cdc42/RacA-C458 to examine the importance of BemA-binding for the function of Cdc42 in symbiotic infection." (PMID 29370294, 2018). "Building on this initial result, we tested additional inhibitors to the Rho family GTPase Cdc42 and the downstream Rho-associated protein kinase (ROCK), both of which also significantly reduced infection." (PMID 28114951, 2017). "The studies discussed here suggest that many RNA viruses share a dependence on Cdc42-signalling to achieve successful infection." (PMID 26690467, 2015). "For example, Salmonella’s SopE and SptP toxins act antagonistically to activate and inactivate Rho-family GTPases CDC42 and Rac1 at different times of infection via a combination of differential activity and temporal stability." (PMID 25774515, 2015). "From a medical point of view, targeting CDC42 is a good approach both for blocking the adaptation of Salmonella in the host cell and abnormal downstream signaling during infection." (PMID 26257716, 2015). "Compared with control shRNA, infection with Cdc42 shRNA reduced the density of PSD-95 puncta in cultures of hippocampal neurons by 24 ± 7%." (PMID 25071442, 2014). "Both infection and endocytic uptake were reduced when some of Cdc42's downstream effectors were inhibited including PAK1 (IPA-3), N-Wasp (wiskostatin), and moderately when Arp2/3 (CK-869) was targeted." (PMID 23593008, 2013). "As expected, activated Cdc42 was detected in FAK-positive cells between 2-4 hours after infection with wt C. jejuni." (PMID 22204307, 2011). "Prominent members are the GTP-binding proteins RhoA, Cdc42 and Rac1, which act as guanine nucleotide-regulated switches to induce various responses during the infection process." (PMID 22204307, 2011). "The generation of filopodia in wt cells confirms the typical occurrence of Cdc42 GTPase activation during infection, followed by dynamic membrane rearrangements and host entry, dependent on the expression of fibronectin, integrin-β1 and FAK." (PMID 22204307, 2011). "The data indicated that maximal levels of kinase activity appeared after 4 hours of infection, which correlated with increasing Cdc42-GTP levels over time and the invasion capabilities of wt C. jejuni, as determined by gentamicin protection assays." (PMID 22204307, 2011). "Nevertheless, we measured the fraction of activated Rac1 and Cdc42 at various times after infection with PAK, PAKΔSΔT, PAKΔS or PAKΔT." (PMID 18369477, 2008). "For example, Cdc42 and actin polymerization are involved in C. caviae entry of mammalian cells, and we show here that their depletion also reduced infection of Drosophila cells." (PMID 17967059, 2007).